IL6 (interleukin 6)
Diseases named in the same sentence as IL6 in open-access papers (continued):
Sharing a sentence is not in itself a finding about the gene and the disease.
Sepsis (continued). "Furthermore, a prospective observational analysis highlighted the exceptional predictive performance of pentraxin 3 (PTX-3), IL-6, PCT, and lactate in predicting 28-day all-cause mortality in sepsis or septic shock patients, outperforming the SOFA score." (PMID 39130839, 2024). "In addition sepsis is accompanied by a cytokine storm, and interleukin-6 IL-6), IL-8, IL-1β, IFN-α2, and IL-33 are released." (PMID 38279209, 2024). "Although it is currently unclear whether IL-6 inhibition has similar benefits in sepsis, a recent Mendelian randomization analysis suggests that IL-6 receptor blockade is associated with lower mortality in 11,643 sepsis patients of the UK Biobank cohort." (PMID 38598083, 2024). "According to our mortality risk predictive model for sepsis, eleven indicators, including a history of CHD, NLR, RDW, lactic acid, PT, PCT, CRP, ALT, Tbil, and IL6 were independent predictors of poor prognosis in patients with sepsis, while the LYMP was a protective factor." (PMID 38765257, 2024). "However, this approach overlooks the broad range of cytokine responses, as illustrated by the finding that IL-6 concentrations vary from 8 to higher than 1.5 million pg/mL among sepsis patients." (PMID 39056754, 2024). "In individuals with sepsis, IL-6 concentrations may increase significantly, reaching up to 1600 pg/mL, whereas in typical adults, the levels typically remain below 7.8 pg/mL." (PMID 38337668, 2024). "“Reversal of immune paralysis” was hypothesized to explain enhanced peripheral blood TNF and IL-6 responses in two clinical trials of macrolide therapy in patients with sepsis." (PMID 39284999, 2024). "Furthermore, in sepsis, B cells can produce a variety of pro-inflammatory cytokines like IL-6, TNF, IL-3, and GM-CSF to reinforce the systemic inflammatory response." (PMID 38474403, 2024). "The use of certain biomarkers such as PCT or IL-6 can help in a rapid diagnosis of true cases of sepsis, due to their high positive predictive value, but it can also help the clinician to rule out infection and thus avoid the use of antibiotics, due to their high negative predictive value." (PMID 38240873, 2024). "Four studies combined the early sepsis marker IL-6 with CRP." (PMID 38671704, 2024). "The mouse model of cytokine storm syndrome (CSS) or sepsis may be particularly useful for testing this hypothesis, given the important roles of IL6 and OSM in CSS pathogenesis." (PMID 38338642, 2024). "Additionally, sepsis is characterized by increased release of pro-inflammatory cytokines, such as IL-1β, IL-6, and TNF-α." (PMID 39337575, 2024). "Additionally, we previously showed that CDNPs are taken up by neutrophils in the CLP model of sepsis, which improved the disease course by lowering IL-6 levels." (PMID 39911575, 2024). "Despite this variability, these findings indicate that IL-6 may be used as a potential biomarker to predict 28-day mortality in sepsis patients." (PMID 39202614, 2024). "In this study, we assembled a cohort of patients with severe trauma and studied several common biomarkers, including PCT, CRP, IL-6 and SAA, with the overall goal of creating a panel that would allow discrimination of ICU patients who are at increased risk of sepsis." (PMID 38182736, 2024). "Sepsis is also related to an increase in bone marrow platelet release, leading to thrombocytosis, which is mediated by elevated levels of platelet growth factors and cytokines such as interleukin-6." (PMID 38273257, 2024). "A recent study demonstrated that serum IL-6 levels could distinguish between sepsis and septic shock." (PMID 38672594, 2024). "IL-6, as an early marker in sepsis, may assist in diagnosing and predicting septic shock outcomes, providing valuable information alongside other parameters commonly used in clinical practice." (PMID 39589972, 2024).
Sepsis (continued). "Moreover, the LPA gene features an IL6 response element, implicating it in systemic inflammatory responses, such as sepsis, which consequently elevates Lp(a) levels." (PMID 39263966, 2024). "Our study demonstrated that IL-6 could be a valuable biomarker for predicting 28 day mortality in sepsis compared with the other biomarkers." (PMID 39202614, 2024). "Vincamine exhibited hepato-protective potential during CLP-induced sepsis via the cross-connection of antioxidant, anti-inflammatory, and anti-apoptotic activities by modulating TNFα/IL-6/IL-1β/Nrf-2/Keap-1 and regulating bax/bcl2/cleaved caspase 3 signaling pathways." (PMID 39174578, 2024). "Additionally, the expression of IL1β, TNFα, and IL6 in BALF from FGF2 KO mice was higher than that in WT mice in the sepsis model." (PMID 39436561, 2024). "Interleukin-6 (IL-6) has moderate accuracy in differentiating sepsis from NIOF." (PMID 39457628, 2024). "However, we also found elevated levels of IL-6 measured from samples remote from sepsis with blood draws for routine laboratory tests." (PMID 38312920, 2024). "Additionally, the production of sepsis stimulates an inflammatory response, encouraging the release of pro-inflammatory cytokines (IL-6 and TNF-), which in turn increases the amount of reactive oxygen species." (PMID 39394109, 2024). "This is the first study to show that the in vitro production of TNF-α and IL-6 by preterm neonatal WB at birth is comparable to term neonatal WB and adult WB after exposure to a broad range of stimuli that are relevant during neonatal sepsis." (PMID 38562936, 2024). "However, its ability to predict mortality or sepsis progression is less robust than other markers, such as sTREM-1 or IL-6." (PMID 39655134, 2024). "The identity of RBC-associated bDNA is influenced — but not entirely explained — by procedural and sequencing contamination, and the identity of bDNA in RBCs from patients with sepsis differs from that of healthy individuals and is correlated with systemic IL-6 concentrations." (PMID 39666381, 2024). "During sepsis, the innate immune system acts as the primary defense for the host, with immune cells like monocytes/macrophages becoming hyperactivated, releasing copious inflammatory cytokines, such as interleukin (IL)-1β, IL-6 and interferon-gamma (IFN-γ)." (PMID 39320524, 2024). "Additionally, men with multiple injuries and those who develop post-trauma sepsis produce increased levels of IL-6, IL-8, and TNF-α." (PMID 38835761, 2024). "We compared the effects of two treatments, antibiotics and FMT, on the levels of inflammatory factors, including the proinflammatory factors TNF-ɑ, IFN-γ, IL-1b, and IL-6, and the anti-inflammatory factor IL-10, in the serum and alveolar lavage fluid of pneumonia-induced sepsis model mice." (PMID 38903943, 2024). "Identified keywords were divided into 13 clusters: #0 blood stream infection, #1 septic shock, #2 interleukin 6, #3 early‐onset sepsis, #4 C‐reactive protein, #5 neonatal sepsis, #6 preterm infant, #7 procalcitonin, #8 Escherichia coli, #9 LOS, #10 mortality, #11 newborn, and #12 management." (PMID 40626245, 2024). "Additionally, PCT, along with biomarkers like N-terminal pro B-type natriuretic peptide (NT-proBNP), interleukin-6 (IL-6), prothrombin time (PT), and thrombin time (TT), is supportive in early sepsis diagnosis and in assessing its progression and prognosis." (PMID 39130839, 2024). "Sepsis is characterized by an inflammatory response triggered by infections, leading to the release of proinflammatory cytokines such as interleukin-1beta (IL-1β), IL-6, and TNF-α." (PMID 38629103, 2024). "Therefore, we propose that MASP-1 triggers traumatic sepsis by activating the IL6/JAK/STAT3 signaling pathways and promoting CD8 T-cell depletion after traumatic injury." (PMID 38384415, 2024).
Sepsis (continued). "Alongside these findings, the trial of the TNF-α mAb afelimomab, known as the RAMESES study, provides a nuanced perspective by demonstrating a modest but significant reduction in 28-day mortality in sepsis patients with IL-6 serum levels higher than 1000 pg/mL." (PMID 39056754, 2024). "However, higher IL-6 values were obtained in patients with septic shock than in patients with sepsis." (PMID 39589972, 2024). "Other studies have proposed that serum amyloid A and cell-free DNA could be used for sepsis screening, while interleukin-6 and high-mobility group Box 1 might be useful for the therapeutic monitoring of sepsis." (PMID 37958065, 2023). "IL-6 is a pivotal inflammatory cytokine substantially upregulated in sepsis." (PMID 38313162, 2023). "In addition to the higher levels of CRP and haptoglobin observed, we found a very significant increase in IL-1Ra, IL-6, and IL-8 in the blood of all animals 24 h after sepsis onset." (PMID 38087374, 2023). "The levels of TNF-α and IL-6 were significantly increased in MRAB 0227-treated sepsis mice." (PMID 37942076, 2023). "It revealed that apoE23 therapy effectively reduced plasma levels of TNF-α, IL-6, and LPS; decreased bacterial load in the spleen tissue homogenate; and alleviated infection-induced lung, liver, and small intestine injuries in mice with sepsis." (PMID 37533741, 2023). "The IL-6 CSF/plasma ratio in neonates with HIE was higher than in neonates with sepsis or normal neonates, suggesting that IL-6 might be produced in the central nervous system, then extravasate into circulating blood." (PMID 36776908, 2023). "Concerning the other variables positively associated with a worse outcome, we must mention age and comorbidities, identified by CCI and NT‐proBNP, as well as biomarkers of inflammation (interleukin 6) and sepsis (procalcitonin and MR, pro‐adrenomedullin), consistent with our recent data." (PMID 37964734, 2023). "LPS and IL-6 have been utilized to induce in vitro models of sepsis in cultured ECs." (PMID 37205094, 2023). "Elevated levels of IL-6 have been shown to be an early marker of sepsis in patients with DKA." (PMID 37102024, 2023). "Interleukin 6 (IL-6) is one of the most important biomarkers in sepsis." (PMID 36836567, 2023). "The levels of proinflammatory cytokines including IL-6, IL-1β, Il-17A and TNF-α, as detected by quantitative PCR or enzyme-linked immunosorbent assay (ELISA), were decreased in lung tissue of sepsis mice upon treatment of JHD, as compared with their counterpart with no treatment." (PMID 37081964, 2023). "Our data are therefore suggestive that functional down-regulation of IL6 may have beneficial effects in improving sepsis outcomes." (PMID 36716318, 2023). "Moreover, the intestines of IL-6-wild-type mice are more vulnerable to sepsis and have increased paracellular and transcellular transport in response compared to mice lacking IL-6 expression." (PMID 38106420, 2023). "Inflammatory hallmark cytokines IL-1β, IL-6, and TNF-α constitute the cytokine storm during sepsis." (PMID 38152336, 2023). "In a sepsis model characterized by significant systemic inflammation, sleep in rats exhibited a fragmented pattern, which was found to be influenced by elevated mRNA and protein levels of cytokines, including IL-1β, IL-6, and TNF-α, in the nervous system." (PMID 37872570, 2023). "IL-6 was frequently found in the blood and lung of patients with sepsis, but the exact role of IL-6 in sepsis is still under investigation, which may be related to the activation of the complement pathway and capillary leakage." (PMID 38035100, 2023). "Elevated levels of IL-6 in serum correlate with decreased survival rate in patients with sepsis." (PMID 38313162, 2023). "Sepsis patients had higher plasma interleukin-6 (IL-6) levels in comparison to the controls." (PMID 38137508, 2023). "IL-6 is a therapeutic target of cytokine release syndrome and sepsis." (PMID 38094883, 2023).
Sepsis (continued). "Relative to the sepsis mice, mice treated with sphinganine exhibited strongly enhanced colon length (p < 0.05), as well as markedly diminished D-lactic acid, IL-1β, and IL-6 contents (p < 0.05)." (PMID 37292192, 2023). "Elevated IL-1β and IL-6 in Alzheimer’s disease echo the neuroinflammation seen in sepsis." (PMID 36844403, 2023). "An extensive body of research reported previously has also highlighted the potential of IL-6 in particular as a biomarker of traumatic injury severity and clinically important outcomes such as; multi-organ dysfunction, sepsis and mortality." (PMID 38077362, 2023). "Significantly higher levels of serum IL-6 (404.54 ± 543.38 vs 185.11 ± 242.73 pg/ml), IL-2 (5.30 ± 2.03 vs 4.11 ± 1.67 pg/ml), and IL-4 (4.76 ± 1.31 vs 3.34 ± 1.37 pg/ml) were found in patients with KD combined with severe sepsis (all P<0.05, respectively)." (PMID 37234775, 2023). "Likewise, omega-3 fatty acids in severe COVID-19 patients with sepsis showed potential benefits, including reduced procalcitonin and IL-6 levels." (PMID 37600769, 2023). "The levels of PCT and IL-6 were correlated with the recovery of sepsis." (PMID 36694784, 2023). "Its production increases in patients with septicemia and infections caused by gram-negative bacteria due to inflammatory cytokines, such as tumor necrosis factor-alpha and interleukin-6 (IL-6)." (PMID 37664550, 2023). "Elevated levels of pro-inflammatory cytokines TNF-α, IL-6 and chemokines are the markers of sepsis." (PMID 37266014, 2023). "Interleukin-1 (IL-1), IL-6, C-reactive protein and other inflammatory mediators stimulate TF expression on the surface of endothelial cells under inflammatory conditions such as sepsis and acute lung injury, leading to hypercoagulability." (PMID 37693903, 2023). "We speculated that it might be related to sepsis toxin, and thus we investigated sIL‐6R, which is the receptor of the IL‐6 trans‐signaling pathway." (PMID 37525933, 2023). "Slighter ARDS, a complexity of extreme sepsis, and sepsis-related fatalities in women than men were associated with high IL-6 levels and independent of age and illness." (PMID 36873532, 2023). "The concentration of IL-6 in peripheral blood were highest in sepsis group and IL-7 antibody treatment could decrease the concentration of IL-6." (PMID 37113759, 2023). "Moreover, we observed relatively high IL-6 levels with regard to existing literature, with maximum serum concentrations greater than 500 pg/ml, comparable to sepsis patients." (PMID 37711559, 2023). "Research suggests that a combination of initial and follow-up IL-6 levels could provide an additional prognostic value for sepsis mortality." (PMID 36383295, 2023). "We can hypothesize that after the early phase of sepsis, where inflammatory markers such as IL-8, IL-6, CRP, or procalcitonin are highly elevated, ATP is also released as a danger signal." (PMID 38094297, 2023). "During sepsis, there may be an unbalanced inflammatory response due to cytokine storm, and IL-1, IL-6, and TNF-alpha may be produced in excessive amounts and may increase the production of other proinflammatory cytokines." (PMID 38275661, 2023). "In a Mendelian randomisation analysis, Fergus Hamilton and colleagues test the hypothesis that blockade of interleukin-6 signalling could improve outcomes in sepsis." (PMID 36716318, 2023). "verified that the miR-125-mediation MCEMP1 suppression could decrease the sera levels of TNF-α, IL-1β, and IL-6, and the programmed cell death facilitated the T leukomonocyte activity, hence attenuating the immune activity of sepsis mice." (PMID 37359526, 2023). "Using interleukin-6 cut-off values of 80 pg/ml on day of life 1, 40 pg/ml on day of life 2–7 and 30 pg/ml after day of life 7, a sensitivity of 75% and a specificity of 81% for culture-confirmed sepsis were achieved." (PMID 36216867, 2023). "For sepsis severity assessment and patient monitoring, IL-6 measurement has become important." (PMID 38275661, 2023).
Sepsis (continued). "The diagnostic value of IL-6 was superior to those of PTX3 and PCT for sepsis and septic shock." (PMID 36878489, 2023). "Due to the fact that during sepsis IL-6 levels usually reach high values, the literature data indicates that they may also be a useful marker in the diagnostics of bacterial infections." (PMID 37509519, 2023). "During sepsis, the abundant presence of PRRs in the circulation activates PAMPs, which initiate a downstream cascade resulting in the release of pro-inflammatory mediators, including IL-1, IL-6, and TNF-α." (PMID 37510681, 2023). "This is particularly acute with respect to the potential definition of a population that might benefit from IL-6 inhibition in the context of the severity of sepsis, but also the possible risks according to other infection risk (especially in the frail)." (PMID 36716318, 2023). "Our results indicated that Daph treatment improved survival rate and alleviated pulmonary pathological damage of the sepsis mice, as well as reduced the excessive release of pro-inflammatory cytokines IL-1β, IL-18, IL-6, iNOS and chemokines MCP-1 regulated by MAPK/NF-κB pathway in pulmonary injury." (PMID 36998049, 2023). "(2019) also showed that AST treatment could attenuate inflammatory factors (TNF-α and IL-6) significantly by inhibiting MAPK/NF-κB signaling pathway in a mouse model of lipopolysaccharide (LPS)-induced sepsis and acute lung injury in vitro and in vivo." (PMID 37020589, 2023). "In addition, the essential role of IL-6 in sepsis-induced acute lung injury and pulmonary arterial hypertension has also been observed." (PMID 38249419, 2023). "The serum IL-6 density was the highest in the control + sepsis 12 h group." (PMID 36982713, 2023). "As IL-6 is also known as a key inflammatory mediator during cytokine storm in sepsis, further investigation of a possible impact of Ruxolitinib, JAK1 and IL-6 in RNase1-associated EC dysfunction might be of future interest." (PMID 37189117, 2023). "Likewise, another study identified a correlation between specific methylation changes in monocytes of sepsis patients, IL-10 and IL-6 levels, and organ dysfunction." (PMID 36844403, 2023). "In studies of cytokines, IL-6 has also been suggested to correlate with the severity of sepsis." (PMID 38035100, 2023). "However, it is found at rather low concentrations in more recent sepsis-3 cohorts, whereas IL-6 appears to be more closely correlated with sepsis pathology and has been thoroughly linked to prognosis." (PMID 37869001, 2023). "This study aimed to determine the effects of MLT application in lipopolysaccharide (LPS)-induced sepsis in Wistar rats by determining the levels of liver tissue pro-inflammatory cytokines (TNF-α, IL-6) and NF-κB as well as hematological parameters indicating the state of sepsis." (PMID 38203627, 2023). "The rise of the CRP concentration in sepsis is primarily induced by interleukin (IL)-6 and IL-1β." (PMID 37744876, 2023). "Noteworthily, IL-6 1 week after sepsis onset, but not CRP, was also independently associated with mortality." (PMID 37241065, 2023). "IL-6 is essential for innate and adaptive immunity and can be a marker for diagnosing sepsis." (PMID 37310657, 2023). "Similarly, levels of IL-6 and IL-1β in the lung tissue were significantly higher (p<0.05) in the sepsis group compared to the sham group." (PMID 37675176, 2023). "Moreover, the pattern of changes in sepsis-induced ALI was comparable to that in lung HSP-70 expression or serum IL-6 levels." (PMID 36982713, 2023). "In patients with sepsis, IL-6 values were found to be elevated persistently, usually >500 pg/mL." (PMID 37366985, 2023). "Several previous studies have demonstrated that IL-6 levels are correlated with sepsis mortality." (PMID 36383295, 2023).